THBS1 (thrombospondin 1)
Diseases named in the same sentence as THBS1 in open-access papers (continued):
Sharing a sentence is not in itself a finding about the gene and the disease.
liver fibrosis (20 papers, 2013 to 2025). "Hepatic knockdown of E2F1 ameliorated the increased liver fibrosis in mice with hepatic Chrebpα deficiency while reducing the expression of hepatic THBS1 and CTGF." (PMID 40548862, 2025). "Therefore, THBS1 may be a potential target gene for regulating liver fibrosis associated with type 2 diabetes." (PMID 40299397, 2025). "The upregulation of THBS1 was observed in both diseases, and it is closely related to the progression of liver fibrosis and T2DM." (PMID 40299397, 2025). "All these genes are involved in promoting fibrotic changes, especially GFAP, TIMP1, and THBS1, which are expressed by activated hepatic stellate cells, thereby driving liver fibrosis (38, –, 40)." (PMID 40793786, 2025). "Like VIM, THBS1 is a marker of liver fibrosis and cirrhosis with important roles in inflammation, cellular adhesion, growth, migration, and angiogenesis." (PMID 36768808, 2023). "It is suggested that THBS1 contributes to liver fibrosis both as an activator of TGFβ and as a modulator of angiogenesis." (PMID 36768808, 2023). "It has been described that level of thrombospondin-1 (THBS-1) is higher in the serum of patients with hepatic fibrosis." (PMID 26317806, 2015). "The two proteins, enolase-1 and thrombospondin-1(TSP-1) were detected by western blot in the serum of hepatic fibrosis patients and HBV carriers." (PMID 23845056, 2013). "Ultimately, THBS1 and IGFBP7 were selected as key genes associated with liver fibrosis and T2DM." (PMID 40299397, 2025). "Molecular biology verified that THBS1 could mediate hepatic fibrosis by participating in the activation of the PDGF/PDGFR signaling pathway, followed by the activation of the JAK2/STAT3 signaling pathway, ultimately mediating liver fibrogenesis." (PMID 41394148, 2025). "It remains unclear whether there is the spatial dynamics between Thbs1+ macrophages and aHSCs during the development of liver fibrosis and how these dynamics contribute to liver tissue homeostasis." (PMID 37724132, 2023). "In addition, we also used immunostaining to evaluate the expression of thrombospondin 1 (Thbs1) and chemokine (C-C motif) ligand 2 (Ccl2), two factors that are known to contribute to inflammation and hepatic fibrosis." (PMID 27226149, 2016). "However, it remains uncertain whether THBS1 directly induces M1 macrophages, thereby accelerating the progression of liver fibrosis." (PMID 40299397, 2025). "THBS1 may function as a pivotal hub protein in RILI-induced hepatic fibrosis." (PMID 41394148, 2025). "To analyze the degree of liver fibrosis in these groups of mice, we performed immunoblotting for α‐SMA, THBS1, and CTGF as well as Sirius Red staining for collagen and immunohistochemistry (IHC) for COL1A1." (PMID 40548862, 2025). "The results indicated that, compared to normal tissue samples, the expression levels of THBS1 were upregulated in the T2DM patients and the liver fibrosis patients." (PMID 40299397, 2025). "Validation confirmed that THBS1 was upregulated in both conditions, while IGFBP7 was mainly elevated in liver fibrosis." (PMID 40299397, 2025). "Next, we examined the impact of Chrebpα manipulation in hepatocytes on the protein expression of THBS1 and CTGF in mouse models of liver fibrosis." (PMID 40548862, 2025). "Our study confirms the critical role of THBS1 in RILI and identifies it as a mediator of hepatic fibrosis in RILI through PDGF/PDGFR and JAK2/STAT3 signaling pathways." (PMID 41394148, 2025). "Ten DEGs including PDGFra, PDGFrb, PDGFb, PDGFd, COL1A1, COL1A2, COL5A2, ITGA5, THBS1 and IL1R1, closely related to liver fibrosis, were chosen for the real-time qRT-PCR analysis." (PMID 26691002, 2015). "HQD down-regulated the expressions of PDGFra, PDGFrb, PDGFb, PDGFd, COL1A1, COL1A2, COL5A2 and THBS1, and TGF-β and PDGF signaling pathways in the DMN-induced liver fibrosis in rats." (PMID 26691002, 2015).
liver fibrosis (continued). "Specifically, THBS1 stands out as a particularly significant gene in this network, with its regulation by both SMC3 and BHLHE40 highlighting its central role in the progression of liver fibrosis and T2DM." (PMID 40299397, 2025). "THBS1 is secreted in response to inflammation, and has been shown to be involved in tissue injury, inflammatory diseases, liver fibrosis and hepatic cancer, but there is no clear evidence regarding the involvement of THBS1 in ACLF pathogenesis and outcome." (PMID 38439091, 2024). "A recent study reveals that the expression of C-myc and Smad2/3 are upregulated in LPS-treated hepatic stellate cells, while the expression of recombinant thrombospondin 1 and phosphorylation of STAT3 is upregulated in the hepatocytes of mice with liver fibrosis." (PMID 36986363, 2023). "The identified subcluster of Thbs1+ macrophages that activate HSC may represent a novel profibrotic mechanism and potential liver fibrosis therapeutic intervention." (PMID 37724132, 2023). "Notably, mRNA expression analysis and triple immunofluorescence staining have demonstrated that Thbs1 is specifically expressed in the profibrogenic Mac1 cluster in mouse and human fibrotic livers, implying that Thbs1 may play a critical role in compromising liver fibrosis." (PMID 37724132, 2023). "Five atrial extracellular matrix (ECM) member proteins form the thrombospondin family, with thrombospondin-1 (TSP-1) being the best known due to its role in inflammation and fibrogenesis in several illnesses, including liver fibrosis, diabetes, various cancers and cardiovascular conditions." (PMID 36012430, 2022). "Importantly, THBS1 activates transforming growth factor (TGF)-β, a key molecule in the development of liver fibrosis and inflammatory renal diseases." (PMID 29296203, 2017).
colon carcinoma (19 papers, 2009 to 2025). "Given its role in delaying angiogenesis, THBS1 has been shown to suppress tumor growth and has also been found to be positively associated with patient survival in several cancers, such as lung, bladder, gastric, and colon cancers." (PMID 34432380, 2021). "Thbs1, which is also overexpressed in the stromal compartment of colon tumors, is thought to contribute to immunosuppression in CRC." (PMID 40772227, 2025). "More relevant to human APC-dependent colon cancers, ApcMin/+:Thbs1−/− mice fed a high-fat diet had a 48% (P<0.02) increase in adenoma formation in the large intestine when compared with ApcMin/+ mice fed the same diet." (PMID 27239962, 2016). "In other cell systems, p38 MAPK mediates MMP-9 upregulation in response to several stimuli, including TNF-α and SDF-1/CXCR7 in bladder and ovarian, respectively, carcinoma cells, and clusterin/thrombospondin-1 in platelet-stimulated colon cancer." (PMID 27829220, 2016). "Conversely, other miRNAs, such as miR-194, are also downregulated in colon cancer, which can directly target an inhibitor of angiogenesis by binding to the 3′ UTR of THBS1 mRNA that encodes thrombospondin-1 (TSP-1)." (PMID 26064956, 2015). "To establish if the mechanism mediating paracrine cellular communication that we uncovered is conserved in human colon cancer, we then analysed a cohort of 10 human colon tumours (five low-grade adenomas and five invasive carcinomas) for their expression of THBS1, LGR5, and YAP." (PMID 35543624, 2022). "Of relevance, THBS1 neutralisation showed a tumour-specific toxicity; we thus propose that THBS1 may represent a therapeutic target for colon cancer, potentially applicable to other epithelial tumours." (PMID 35543624, 2022). "MTO-derived tumors exhibited enhanced stromal activation, as indicated by abundant collagen deposition, accompanied by increased THBS1 expression, in contrast to tumors derived from MC38, a widely used mouse colon tumor cell line resembling immunogenic CRC." (PMID 37749092, 2023). "Correlation analyses using TCGA data showed that THBS2 is significantly positively correlated with THBS1, THBS3, THBS4, and THBS5 in colon cancer." (PMID 34804159, 2021). "These miRNAs have been shown to mediate the proangiogenic effect of MYC by decreasing the THBS1 (particularly for miR-19a) and CTGF mRNA (particularly for miR-18a) half-life, thereby promoting tumor growth in vivo in a mouse colon carcinoma model." (PMID 22383169, 2012). "A number of chemotherapeutic agents such as 5-FU and trastuzumab up-regulate THBS-1, with 1 mol l−1 of 5-FU up-regulating the level of THBS-1 three-fold in KM12C human colon carcinoma cells and two-fold in HUVEC and human colon adenocarcinoma LOVO cells." (PMID 19738618, 2009). "Importantly, we show that the THBS1/YAP1 signalling axis we discovered in organoids is conserved in both mouse and human colon cancer and propose that this early mechanism of non-cell-autonomous epithelial communication is critical for the establishment of a primary tumour." (PMID 35543624, 2022).
pancreatic cancer (17 papers, 2007 to 2026). "For example, restoration of canonical TGF-β signaling in SMAD4-deficient pancreatic cancer cells (PCCs) has been reported to suppress angiogenesis by up-regulating anti-angiogenic thrombospondin-1 (THBS1), and we detected a 5.63-fold increase in THBS1 in patients with a strong angiogenic signature." (PMID 26586478, 2016). "Overexpression of CDC6 significantly promoted glycolysis and tumor progression in pancreatic cancer, whereas these pro-tumor effects were markedly abrogated by THBS1 knockdown." (PMID 42014675, 2026). "THBS1 rs2228263 has been investigated in several diseases such as coronary artery disease, pancreatic cancer and sickle cell anemia." (PMID 34575042, 2021). "CAFs in pancreatic cancer form annexin A6/LDL receptor-related protein 1/thrombospondin 1 (ANXA6/LRP1/TSP1) complex, which is released in the form of extracellular vesicles (EVs), thereby enhancing the migratory capacity of cancer cells, which ingests EVs." (PMID 33050237, 2020). "Simultaneously, one observation suggested that metronomic ceramide analogs (C2 and AL6) inhibited angiogenesis in pancreatic cancer through up-regulation of THBS1." (PMID 31412643, 2019). "THBS1 was significantly decreased in pancreatic cancer patients compared with healthy controls, and low levels of THBS1 were markedly correlated with poorer survival, preclinically and at clinical diagnosis." (PMID 31412643, 2019). "Studies in mouse models of breast and pancreatic cancer showed that losartan reduces intratumoral expression of thrombospondin-1 (THBS-1), an activator of transforming growth factor beta (TGF-β), resulting in a significant decrease in intratumoral collagen and hyaluronan." (PMID 41596584, 2026). "Moreover, POSTN and THBS1 are related to pancreatic cancer development and patient survival." (PMID 38029961, 2024). "Yet, in the first clinical validation we observed significantly lower THBS1 expression in PDAC cases relative to controls, and this phenomenon has been reported in pancreatic cancer patients up to 24 months prior to diagnosis." (PMID 41294700, 2025). "The predictive potential of THBS1 and MMP9 for the prognosis of pancreatic cancer has been reported in a few previous studies." (PMID 29515771, 2018). "Collectively, our findings demonstrate that CDC6/THBS1/AKT signaling drives glycolysis and accelerates pancreatic cancer progression, suggesting that the CDC6/THBS1/AKT axis may serve as a promising therapeutic target for pancreatic cancer." (PMID 42014675, 2026). "In pancreatic cancer, THBS2 is correlated with THBS1, THBS3, and THBS5." (PMID 34804159, 2021). "Smad4 target genes previously identified in colorectal and pancreatic carcinoma cells, namely E-cadherin, laminin-5, VEGF and thrombospondin-1, were not affected through Smad4 reexpression in C4-II cervical cancer cells (data not shown)." (PMID 17997817, 2007). "Target genes involved in the Smad4-mediated tumour suppression in colorectal and in pancreatic carcinoma cells, such as E-cadherin, laminin-5, VEGF and thrombospondin-1, however, did not respond to Smad4-reexpression in C4-II cervical cancer cells." (PMID 17997817, 2007).
bladder cancer (14 papers, 2006 to 2025). "Among these, two (EGFR and THBS1) were associated with bladder cancer based on Kyoto Encyclopedia of Genes and Genomes (KEGG) pathway enrichment analysis." (PMID 40833781, 2025). "In murine bladder cancer models, androgen has been found to create a microenvironment that promotes tumor growth by inhibiting thrombospondin-1, an antiangiogenic factor." (PMID 39409958, 2024). "Suppression of THBS1 enhances the progression, invasion, and migration of bladder cancer." (PMID 35984577, 2022). "Therefore, four overlapping genes (EGF, EGFR, VEGFA, and THBS1) were extracted from the bladder cancer and PI3K–AKT pathways." (PMID 30868054, 2019). "The results of the analysis showed that seven genes (VCL, FLNA, THBS1, TAGLN, ACTA2, COL6A2, and CALD1) were significantly correlated (P < 0.05) with the prognosis of bladder cancer patients, and these genes were included in the subsequent in-depth study." (PMID 41181151, 2025). "In urinary bladder cancer patients, castration reduces tumor cell growth by DHT in vivo and decreases thrombospondin-1 (TSP1) expression." (PMID 32326308, 2020). "Accordingly, we select the intersection of two gene sets, namely the bladder cancer and PI3K–Akt pathways, which then generates four common genes, EGF, EGFR, THBS1, and VEGFA (EntrezGene ID: 1950, 1956, 7057, 7422)." (PMID 30868054, 2019). "We have previously shown reduced expression of thrombospondin-1 in a mouse model and in human bladder cancer relative to normal urothelium." (PMID 22898175, 2012).
myocardial infarction (14 papers, 2016 to 2025). Gross necrosis of the myocardium, as a result of interruption of the blood supply to the area, as in coronary thrombosis. "A common THBS1 variant (N700S, minor allele frequencies of 0.12 in White Europeans) may modify the risk of myocardial infarction and may contribute to small infant size." (PMID 36453543, 2022). "Thrombospondin-1 is a component of extracellular matrix that acts as a negative regulator of angiogenesis and is associated with cardiovascular disease where its elevation is seen in cardiac insults such as myocardial infarction." (PMID 34248840, 2021). "In conclusion, to the best of our knowledge, this is the first study to propose that M2-exos deliver miR-132-3p to ECs, and enhanced the angiogenic ability of ECs by down-regulating THBS1, thereby promoting angiogenesis after myocardial infarction." (PMID 38840223, 2024). "These genes were previously reported to protect the failing heart from adverse remodeling and dysfunction (Thbs1 and Sparc) or involved in collagen maturation and matrix production in reparative post-myocardial infarction (MI) (Emilin1 and Postn)." (PMID 35203431, 2022). "In a myocardial infarction model, Thbs1 -/- mice display more intense and diffuse inflammation surrounding the infarcted area of the heart." (PMID 33854480, 2021). "In rats, chronic ADO administration can increase border-zone vascularization of myocardial infarction lesions, via increase thrombospondin-1 expression." (PMID 28333936, 2017). "THBS1 has been shown to increase 24 h acutely following myocardial infarction." (PMID 35109843, 2022). "In addition, THBS1 was reported to be a shared biomarker between myocardial infarction and OA." (PMID 41169411, 2025). "Additionally, THBS1 was shown to reduce vascular remodeling following myocardial infarction." (PMID 35109843, 2022).